ATP7A (ATPase copper transporting alpha)
Diseases named in the same sentence as ATP7A in open-access papers (continued):
Sharing a sentence is not in itself a finding about the gene and the disease.
Menkes disease (continued). "Using fibroblasts from Menkes disease patients and mouse 3T3-L1 cells with a CRISPR/Cas9-inactivated ATP7A, we demonstrate that ATP7A dysfunction is also damaging to mitochondrial redox balance." (PMID 27226607, 2016). "The striking differences between Menkes disease, OHS and SMAX3, particularly in the affected organs, highlights the need to understand the functions of ATP7A at a tissue-specific level." (PMID 22900086, 2012). "ATP7A is required to facilitate copper transport across the BBB, and the neurological characteristics of Menkes disease are present in early infancy and emphasize a critical role of copper in neuronal development." (PMID 23055972, 2012). "Glutaredoxin (thioltransferase), or GLRX, regulates the activity of the copper-transporting P-type ATPases ATP7A and ATP7B that are involved in Menkes disease (OMIM: #309400) and Wilson disease (OMIM: #277900), respectively." (PMID 21858011, 2011). "ATOX1 transfers Cu+ to membrane-bound Cu(I) exporters, the Cu-ATPases ATP7A and ATP7B, also known as the Menkes disease protein and Wilson’s disease protein, respectively, due to their deficiencies eliciting the respective pathobiochemical alterations in humans." (PMID 38727263, 2024). "Variability in phenotype between the brothers was attributed to greater upregulation of ATP7A transcription in fibroblasts from the more mildly affected brother with the OHS phenotype, compared to his more severely affected brother with a Menkes syndrome phenotype." (PMID 38141875, 2024). "Cu uptake is blocked in peripheral tissues such as in blood cells in Menkes disease for ATP7A mutants, and in the mutants Cu is failed to be pump to the circulation system from enterocytes." (PMID 37009226, 2023). "A lack of activity of the ATP7A protein leads to copper accumulation in the kidney of the mottled mice and patients with Menkes disease." (PMID 36232742, 2022). "In Proband 5, a girl with Menkes disease, the BCT disrupted the ATP7A gene." (PMID 32344861, 2020). "Questions that we hope to address with this new animal model include the extent to which the neurological abnormalities in Menkes disease arise from a lack of copper delivery from the blood into the brain, versus a lack of ATP7A within the brain itself." (PMID 22900086, 2012). "Further studies in human Menkes' disease fibroblasts that do not express either transporter and in sublines molecularly engineered to express either ATP7A or ATP7B demonstrated that these transporters influence the pharmacodynamics of cisplatin, carboplatin, and oxaliplatin." (PMID 24278698, 2012). "Therefore, endemic variance does not adhere to the ATP7A gene and the incidence is the same worldwide, but diagnosing Menkes disease may vary." (PMID 36995557, 2023). "Despite the new cellular/molecular connections outlined here for copper-dependent processes, the Menkes disease enzyme puzzle, linking consequences of ATP7A dysfunction in cells and tissue to MNK patients’ clinical symptoms, is not yet complete." (PMID 33917579, 2021). "As there are currently no effective treatments for Menkes disease, occipital horn syndrome or SMAX3, deciphering the phenotypic of consequences tissue-specific Atp7a deletion may lead to new therapies for these disorders." (PMID 22900086, 2012).
occipital horn syndrome (40 papers, 2008 to 2026). Occipital horn syndrome (OHS) is a mild form of Menkes disease (MD), a syndrome characterized by progressive neurodegeneration and connective tissue disorders due to a copper transport defect. "Mutations affecting ATP7A also cause occipital horn syndrome and a rare form of adult-onset motor neuropathy, further emphasising the need for available copper in the CNS." (PMID 39164165, 2024). "The clinical phenotypes of ATP7A gene reported in the literature were X-linked Menkes disease, occipital horn syndrome, distal spinal muscular atrophy 318–20." (PMID 35715422, 2022). "ATP7A mutations also underlie occipital horn syndrome (OHS), a milder disease with moderate neurologic symptoms and prominent connective tissue disturbances." (PMID 24904274, 2014). "Occipital horn syndrome is also caused by mutations in ATP7A, but it is a milder disease with primarily connective tissue defects and moderate neurological symptoms." (PMID 23986700, 2013). "Variants in the ATP7A gene can cause milder disease, occipital horn syndrome (OHS) [OMIM #304150], and X-linked motor neuron disease (SMAX3) [OMIM #300489]." (PMID 36995557, 2023). "Occipital horn syndrome (OHS) is a rare connective tissue disorder caused by pathogenic variants in ATP7A, encoding a copper transporter." (PMID 31336972, 2019). "Occipital horn syndrome (OHS) is a milder allelic form that is caused by partial loss of function of the ATP7A gene." (PMID 28443131, 2017). "Occipital horn syndrome (OHS) is a rare genetic disease and copper transport disorder caused by a faulty ATP7A gene with multisystemic presentations, most originally related to musculoskeletal and connective tissue affections." (PMID 39544917, 2024). "For example, mutation of ATP7A, a TGN-localised ATP-driven copper ion pump, causes occipital horn syndrome (OHS), an X-linked recessive disorder that affects the connective tissue, skeleton and nervous system." (PMID 35023559, 2022). "Partial ATP7A gene duplication was identified in 20 unrelated patients including one patient with Occipital Horn Syndrome (OHS)." (PMID 22074552, 2011). "For example, a recent long-read sequencing study identified a 2.8 kb SVA retrotransposon insertion deep within an intron of ATP7A in a 16-year-old boy with occipital horn syndrome (OHS)." (PMID 41393994, 2025).
Wilson disease (39 papers, 2011 to 2025). A very rare inherited multisystemic disease presenting non-specific neurological, hepatic, psychiatric or osseo-muscular manifestations due to excessive copper deposition in the body. "As a copper exporter, a mutation of ATP7A results in Wilson’s disease, however studies relating ATP7A mutations with HCC are rare." (PMID 36408192, 2022). "This difference is underscored by the two genetic disorders, Menkes and Wilson diseases, which are caused by mutations in ATP7A and ATP7B, respectively, and lead to very different clinical manifestations." (PMID 31540259, 2019). "It is interesting to note that Menkes and Wilson’s disease with mutations of gene coding ATPase copper-transporting alpha and beta polypeptides (ATP7a, ATP7b) respectively, i.e., copper deregulation features neurodegeneration." (PMID 30498443, 2018). "Mutations in copper transporters ATP7B and ATP7A result in, respectively, Wilson’s disease (WD) (characterized by copper overload) and Menkes disease (characterized by systemic copper deficiency and fatal in childhood)." (PMID 29976696, 2018). "Here, we report an ATP7A mutation, manifesting with an unusual complex phenotype resembling Wilson disease." (PMID 27878136, 2016). "Another copper transporter ATP7A is critical for many physiological processes, whereas dysregulation of ATP7A function has been associated with copper‐related metabolic disorders, including Menkes and Wilson diseases." (PMID 34390123, 2021). "Inactivating mutations in ATP7A and ATP7B lead to Menkes disease and Wilson disease (WD), respectively." (PMID 38715962, 2024). "While ATP7A mutations cause Cu deficiency resulting in developmental delay, hypotonia, and nervous system deterioration, mutations in ATP7B cause Wilson’s disease that results in excessive Cu accumulation, mainly in the liver and brain." (PMID 36818345, 2023). "Mutations in ATP7A and ATP7B genes cause inherited disorders, known as Menkes and Wilson diseases, respectively." (PMID 36818345, 2023). "Considering that dysfunction of these transporters causes serious abnormalities of Cu homeostasis in Menkes and Wilson diseases, it would be extremely important to target ATP7A and ATP7B in a tumor-restricted manner." (PMID 31540259, 2019). "The Cu-transporting ATPase encoded by CCC2 is the yeast ortholog of human ATP7A and ATP7B, mutations in which cause Cu homeostasis defects linked to Menkes’ and Wilson's diseases, respectively." (PMID 28867595, 2017). "Furthermore, based on the observations in the Labrador retrievers, mutations in ATP7A, with a subtle effect, may be involved as modifiers in Wilson disease and may explain part of the observed difference in ATP7B mutation frequency and presence of clinical disease." (PMID 26861285, 2016). "ATP7A- and ATP7B-deficiency, due to genetic mutation, underlie the inherited copper transport disorders, Menkes and Wilson diseases, respectively." (PMID 23986700, 2013). "Mutations of ATP7A and ATP7B genes cause Menkes’ and Wilson’s diseases, respectively." (PMID 38136617, 2023). "Pathogenic variants in ATP7A and ATP7B manifest as Menkes and Wilson disease, respectively." (PMID 36301669, 2023). "Human ATP7A and ATP7B are the best studied examples of the universally conserved P1B-type ATPases and are linked to the Cu metabolism disorders Menkes disease and Wilson disease." (PMID 32962054, 2020). "When we translate our observations in the Labrador retrievers to the human disease, we might think of ATP7A as a possible modifier gene in Wilson disease." (PMID 26747866, 2016). "In a recent pilot study, two SNPs in ATP7A were genotyped in humans with Wilson disease." (PMID 26747866, 2016). "Variations in ATP7A with a small effect on protein function might reduce the rate of copper accumulation in humans with Wilson disease, thereby modifying the disease phenotype, for example by delaying the age at onset of clinical symptoms." (PMID 26747866, 2016).
Wilson disease (continued). "We recommend genetic screening for ATP7A mutations in patients who manifest clinical symptoms of Wilson disease without mutations in ATP7B." (PMID 27878136, 2016). "Copper dyshomeostasis can occur as a result of genetic dysregulation of copper-transporting ATPase alpha (ATP7A) or beta (ATP7B) leading to Menkes' and Wilson's disease, respectively, or due to environmental factors that contribute to other disorders." (PMID 39970778, 2025). "Since neutrophils from Wilson disease mice lack functional ATP7B, they might still be able to efflux excessive copper via ATP7A." (PMID 32010131, 2019).
breast carcinoma (28 papers, 2005 to 2025). "It has also been shown in mouse mammary carcinoma cells that downregulation of ATP7A led to the loss of LOX-mediated phosphorylation of focal adhesion kinase 1 (FAK1), a key regulator of tumor cell adhesion and motility." (PMID 40721800, 2025). "High expression of ATP7A in breast cancer was significantly linked with reduced survival, while ATP7B showed no statistical difference." (PMID 39676279, 2024). "In breast cancer, ATP7A suppression can impede the function of LOX, a modulator of extracellular matrix (ECM) remodeling, which can consequently lead to tumor cell migration." (PMID 38918694, 2024). "The silencing of Atox1 expression resulted in a decrease in LOX activity and inhibited the migration of breast cancer cells, indicating that ATOX1’s role in the ATP7A–LOX signaling pathway is associated with metastasis." (PMID 38918694, 2024). "It plays a role in facilitating breast cancer cell migration through the coordinated transport of copper in the ATP7A‐LOX axis." (PMID 39676279, 2024). "Recent studies have found that the higher expression of copper transporter ATP7A can promote tumorigenesis and metastasis, and is significantly related to the poor prognosis of breast cancer patients." (PMID 38898987, 2024). "In breast cancer samples, ATP7A (18%), amyloid beta precursor protein (APP) (11%) and ATP7B (9%) were the more frequently mutated genes." (PMID 37180167, 2023). "The expression of ATP7A in breast cancer tissues is significantly higher than that in normal tissues, and inhibiting the expression of ATP7A can improve the sensitivity of breast cancer to cisplatin." (PMID 37608927, 2023). "This study indicated the overexpression of miR-148a-3p negatively regulates ATP7A, which will increase the sensitivity of breast cancer cells to cisplatin." (PMID 36925927, 2023). "In an orthotopic mouse model of breast cancer, ATP7A silencing attenuated LOX activity and reduced the recruitment of myeloid cells to the lungs, thereby suppressing tumor metastasis." (PMID 37767404, 2023). "Decreased expression of the copper exporters ATPase copper transporting α (ATP7A) and ATPase copper transporting β (ATP7B) have been associated with decreased chemotherapy resistance in breast cancer cells." (PMID 37180167, 2023). "In breast cancer cell MDA-MB-231 with ATP7A knocked out, the ability of cisplatin to reduce cell proliferation was enhanced." (PMID 36925927, 2023). "In a mouse model of breast cancer in situ, silencing of ATP7A inhibited the activity of LOX, thus rendering the LOX-dependent metastatic mechanism ineffective in breast cancer cell lines." (PMID 37427098, 2023). "Using the CCK-8 assay, we found down-regulated expression level of ATP7A significantly suppressed the proliferative ability of breast cancer cells." (PMID 35979353, 2022). "Transwell cell migration assay revealed significantly decreased migrated cell numbers in ATP7A-knockdown breast cancer cells compared with control group." (PMID 35979353, 2022). "Taken together, the down-regulation of ATP7A expression markedly restrained proliferation and migration capacities of breast cancer cells, which is in consistent with its pro-tumorigenic role for patients with breast cancer." (PMID 35979353, 2022). "Individual cell migration is an early step in breast cancer metastasis; thus, ATOX1 silencing decreases the breast cancer cell migration velocity via coordinated copper transport in the ATP7A-LOX (proenzyme of lysyl oxidase) axis." (PMID 34504870, 2021). "Next, we will explore what factors regulate ATP7A levels and the mechanism of ATP7A upregulation induced by cisplatin in breast cancer." (PMID 32508020, 2020). "Taken together, these data suggested the miR‐148a‐3p/ATP7A axis which participates in the sensitivity to cisplatin and presents a potential target in breast cancer treatment." (PMID 32508020, 2020).
breast carcinoma (continued). "Then, we investigated the roles of ATP7A and ATP7B in proliferation of breast cancer cells by transfecting ATP7A or ATP7B siRNAs into MDA‐MB‐231 and T47D cells, respectively." (PMID 32508020, 2020). "Immunostaining, flow cytometry, and IC50 assay were utilized to examine the effects of ATP7A‐siRNA combined with cisplatin on apoptosis in breast cancer cells." (PMID 32508020, 2020). "We observed a significant increase in drug efficacy in cisplatin‐resistant breast cancer cells through combining ATP7A‐siRNA with cisplatin." (PMID 32508020, 2020). "In summary, the present study identified copper efflux transporter ATP7A, as a novel target of miR‐148a‐3p, played a critical role in resistance of breast cancer cells to cisplatin via sequestering and pumping cisplatin out of cancer cells." (PMID 32508020, 2020). "The ATP7A protein plays an important role in the formation of metastases in breast cancer and induces the migration of vascular smooth muscle cells." (PMID 33271772, 2020). "The nuclear localization of Atox1 was also correlated with increased migration capabilities in breast cancer cells in an ATP7A- and LOX-dependent mechanism." (PMID 33271772, 2020). "Our previous researches have demonstrated that ATP7A is involved in cisplatin resistance in breast cancer." (PMID 32508020, 2020). "As we studied above, knocking‐down ATP7A increased the sensitivity of breast cancer cells to cisplatin." (PMID 32508020, 2020). "Our results highlight that inhibition of ATP7A is a potential strategy for targeting breast cancer resistant to cisplatin, and we provided an interesting method to compare the involvement of various genes in the assessment of cisplatin resistance." (PMID 32508020, 2020). "Mapping of gene expression signatures in breast cancer cell lines has noted ATP7A as well as LOX as upregulated genes." (PMID 28425924, 2017). "Pharmaceutical replacement for ATP7A by ammonium tetrathiomolybdate (TM) enhanced cisplatin treatment in breast cancer cells." (PMID 27806319, 2016). "Herein, we describe how ATP7A specifically contributes to cisplatin resistance in breast cancer, and how combining cisplatin and ammonium tetrathiomolybdate (TM), which degrades ATP7A, to sensitizes breast tumor cells to cisplatin." (PMID 27806319, 2016). "In this study, we focused on elucidation of the specific biological roles of ATP7A in cisplatin resistant breast cancer." (PMID 27806319, 2016). "We observed a significant increase in drug efficacy in platinum resistant breast cancer cells when we combined RNAi directed at ATP7A with cisplatin." (PMID 27806319, 2016). "In contrast, cells isolated from cisplatin/TM double treated mammary tumors had significantly lower amounts of ATP7A and the protein was frequently observed to be localized in distinct, punctuate regions of the cell." (PMID 27806319, 2016). "We observed key differences between cisplatin localization, and ATP7A protein expression and distribution in the mammary tumor cells." (PMID 27806319, 2016). "In breast cancer, inhibition of ATP7A disrupts LOX activity and impedes metastasis." (PMID 38662225, 2024). "It was found that ATP7A increased the resistance of breast cancer cells to cisplatin and could be inhibited by miR‐148a‐3p to increase the cytotoxicity of cisplatin." (PMID 39676279, 2024). "PDA‐DTC/Cu is a nanoparticle that assembles copper ions into polydopamine nanostructure, which can not only induce cuproptosis in breast cancer by increasing intracellular copper ion content, but also inhibit the expression of ATP7A/B, and further promote the occurrence of cuproptosis." (PMID 39676279, 2024). "Additionally, it was discovered via research of the impact of gene expression patterns on overall survival in breast cancer that those expressing high levels of ATP7A, DBT, DLAT, DLD, GLS, PDHA1, and SLC31A1 had a bad prognosis." (PMID 36059516, 2022). "ATP7A promotes tumor growth and metastasis in lung and breast cancers." (PMID 36568224, 2022).